TREM2 (triggering receptor expressed on myeloid cells 2)
Diseases named in the same sentence as TREM2 in open-access papers (continued):
Sharing a sentence is not in itself a finding about the gene and the disease.
intracerebral hemorrhage (11 papers, 2020 to 2025). A cerebrovascular disorder characterized by bleeding into one or both cerebral hemispheres including the basal ganglia and the cerebral cortex. "The activation of TREM2 reduces neuroinflammation and neuronal apoptosis induced by intracerebral hemorrhage in rats through the PI3K/Akt axis." (PMID 40918528, 2025). "It was reported that TREM2 was expressed not only on microglia but also on astrocytes and neurons in a mouse model of intracerebral hemorrhage." (PMID 39758888, 2024). "Specifically, recent study has demonstrated that the COG1410, an APOE-mimic peptide, strongly alleviates the neuroinflammation and neuronal apoptosis in mice with intracerebral hemorrhage, and TREM2/PI3K/Akt signal pathway involved in the cellular events." (PMID 37658943, 2023). "TREM2 inhibits neuroinflammation and neuronal apoptosis via the PI3K/AKT pathway after intracerebral hemorrhage in mice." (PMID 39420836, 2024).
Hepatic steatosis (10 papers, 2019 to 2025). Steatosis is a term used to denote lipid accumulation within hepatocytes. "A recent study further proved this finding and reported that Trem2 deficiency exacerbates hepatic steatosis in a fat and cholesterol level-independent manner." (PMID 35658903, 2022). "The liver tissue obtained from the MASH patient group and the control group with hepatic hemangioma, which is known not to have been diagnosed with MASH, shows that the upregulation of TREM2 in MASH patients is associated with hepatic steatosis and inflammation." (PMID 40438102, 2025). "Moreover, restricting the increase in serum ceramides reversed adipocyte hypertrophy and hepatic steatosis in Trem2-deficient animals." (PMID 35658903, 2022). "Prior studies have shown that Trem2-/- mice exhibit more severe hepatic steatosis after long-term high-fat diet feeding." (PMID 40242752, 2025). "When fed WD+30% fructose in drinking water (FrWD), both WT and Trem2−/− littermates had similar gains in body and liver weight liver injury and hepatic steatosis." (PMID 39172787, 2024). "Inhibiting ceramide synthesis has been found to attenuate IR and to reverse adipose hypertrophy and secondary hepatic steatosis in Trem2-/- mice." (PMID 35658903, 2022). "Moreover, it has been reported that Trem2−/− mice fed a long-term high fat diet develop more severe hepatic steatosis." (PMID 40438102, 2025). "The histopathology of livers showed more severe hepatic steatosis in TREM2−/− mice than WT mice on HFD, while in CFD mice TREM2 deficiency failed to promote hepatic steatosis." (PMID 31477129, 2019). "The Trem2 gene is highly expressed in Kupffer cells from diet-induced NASH mouse livers and TREM2 mRNA levels are increased in livers from patients with hepatic steatosis and NASH." (PMID 31614590, 2019). "During MASH regression, absence of TREM2+ macrophages not only prevented efficient collagen resorption but also affected elimination of hepatic steatosis and HSC inactivation, indicating their significance in metabolic coordination with other cell types." (PMID 39172787, 2024). "Strikingly, while Foz/Foz mice successfully eliminated >50% of hepatic fat deposits by 8 wk of WD to chow switch, Foz::Trem2−/− mice failed to eliminate hepatic steatosis and had higher liver weights compared to Foz/Foz regression mice." (PMID 39172787, 2024). "Lack of TREM2+ macrophages also prevented elimination of hepatic steatosis and inactivation of HSC during regression, indicating their significance in metabolic coordination with other cell types in the liver." (PMID 39172787, 2024). "The absence of TREM2 did not affect body weight, liver weight, liver injury, or liver steatosis." (PMID 39172787, 2024). "The absence of TREM2 inhibited the regression of hepatic steatosis as well as HSC inactivation." (PMID 39172787, 2024). "Absence of TREM2+ macrophages not only diminishes collagen resorption but also disrupts the metabolic coordination with other cell-types, leading to ineffective hepatic stellate cell inactivation and elimination of hepatic steatosis during regression." (PMID 39172787, 2024). "Importantly, however, myeloid-cell-specific deletion of Trem2 (Trem2ΔMye, generated by crossing Trem2-Floxed mice with Lyz2-Cre) did not affect gain of liver and body weight or hepatic steatosis (similar to our observation)." (PMID 39172787, 2024).
ischemia (10 papers, 2017 to 2024). A hypoperfusion of the BLOOD through an organ or tissue caused by a PATHOLOGIC CONSTRICTION or obstruction of its BLOOD VESSELS, or an absence of BLOOD CIRCULATION. "Pro-inflammatory cytokine levels were also decreased in TREM2 deficient mice after traumatic brain injury, ischemia, lung infection, and demyelination, where TREM2 deficient brain myeloid cells showed a less activated morphology." (PMID 37917301, 2024). "This may be true in diverse disease contexts as pro-inflammatory cytokine levels were also reduced in TREM2 deficient mice following traumatic brain injury, ischemia, lung infection and demyelination, where TREM2 deficient brain myeloid cells exhibited a less activated morphology." (PMID 28768545, 2017). "Collectively, these findings suggest that PE modulates microglial state after ischemia in sub-acute and remote phases in a TREM2-dependent manner.." (PMID 36829205, 2023). "TREM2 has been investigated as a phagocytic receptor and immune receptor in microglia in the ischemia model and AD." (PMID 33081801, 2020). "Taken together, a tempering role of TREM2 signaling in pro-inflammatory pathways and a critical protective role for TREM2 in ischemia-induced neuronal injury is suggested." (PMID 31379859, 2019). "Several reports analyzed TREM2 function in the mouse middle cerebral artery occlusion model of ischemia, in which the microglial number significantly increases in the ischemic hemisphere." (PMID 30127720, 2018). "Additionally, immunofluorescence staining revealed the significantly elevated proportion of IGF1+ and TREM2+ microglia after ischemia, further confirmed those molecular signatures identified by snRNA‐seq and Bulk‐RNA‐Seq analysis." (PMID 38151703, 2024).
liver cancer (10 papers, 2017 to 2025). An epithelial or non-epithelial malignant neoplasm that arises from the liver. "In our study, we found that liver cancer patients with high TREM2 expression have a lower survival rate." (PMID 39697329, 2024). "Echinacoside shows strong effectiveness against liver cancer by reducing the levels of the triggering receptors expressed on myeloid cells 2 (TREM2) and influencing the phosphatidylinositol-3-kinase/protein kinase B (PI3K/AKT) signaling pathway." (PMID 38732450, 2024). "TREM2 methylation level was a protective factor in patients with mesothelioma, uveal melanoma, and liver cancer, in terms of OS." (PMID 33679809, 2021). "TREM2 was first studied in the liver cancer cell lines MHCC97H and HepG2, and the expression level was high." (PMID 33297569, 2020). "Moreover, some researchers found that TREM2 is highly expressed in TAMs in non-small cell lung cancer and liver cancer patients, suggesting that the high expression of TREM2 is associated with poor prognosis of tumor patients." (PMID 36713360, 2022). "Upregulated TREM2 expression levels in liver cancer compared to nontumor tissues were validated in the TCGA-LIHC and GSE14520 datasets." (PMID 35359989, 2022).
pulmonary fibrosis (10 papers, 2022 to 2026). Chronic progressive interstitial lung disorder characterized by the replacement of the lung tissue by connective tissue, leading to progressive dyspnea, respiratory failure, or right heart failure. "Recent research has shown that in patients with IPF and bleomycin (BLM)-induced pulmonary fibrosis in mouse models, the TREM2 expression is significantly elevated and associated with poor prognosis." (PMID 40242752, 2025). "This study aimed to explore the role of TREM2 in regulating ILC activation in bleomycin (BLM)-induced pulmonary fibrosis." (PMID 41928407, 2026). "Further research has revealed that TREM2 deficiency can inhibit STAT6 activity and reduce anti-inflammatory macrophage polarization, thereby exerting a protective effect against pulmonary fibrosis." (PMID 40242752, 2025). "In hypoxic conditions, pulmonary fibrosis can be triggered if Gal-3 binds to the triggering receptor expressed on myeloid cells 2 (TREM2) and activates it." (PMID 38540252, 2024). "In conclusion, TREM2 decreases ILC activity to reduce BLM-induced pulmonary fibrosis." (PMID 41928407, 2026). "Besides Spp1, the macrophage-specific deletion of Trem2, another gene differentially expressed by Gpnmb+Spp1+ macrophages, has been reported to reduce fibrosis in mouse models of pulmonary fibrosis and myocardial infarction." (PMID 40869418, 2025). "Our analysis suggested that Gpnmb and Trem2 were both upregulated in macrophages and may play important roles in pulmonary fibrosis progression." (PMID 37771586, 2023). "Moreover, Gpnmb and Trem2 upregulation in macrophages was found to potentially have important roles in the progression of pulmonary fibrosis." (PMID 37771586, 2023). "However, the relationship between TREM2 and ILCs in pulmonary fibrosis is unclear." (PMID 41928407, 2026). "Notably, TREM2 also promotes lung fibrosis via protecting against macrophage apoptosis, while itaconate secreted by TREM2+ macrophages prevents apoptosis in cardiomyocytes and stimulates the growth of fibroblasts, which in turn enhances the process of cardiac tissue repair." (PMID 40977736, 2025). "CD9+TREM2+ macrophages expressing GPNMB, SPP1, FABP5, and CD63 were reported in murine and human pulmonary fibrosis, enriched at the edges of scars." (PMID 37756565, 2023). "We first examined the role of TREM2 in regulating ILC expression in a mouse model of BLM-induced pulmonary fibrosis, and subsequently assessed the levels of ILCs, pulmonary fibrosis, and inflammation using histological staining and molecular biology techniques." (PMID 41928407, 2026). "However, CD9+TREM2+CD63+ SAMs expressing Spp1 present in liver and lung fibrosis were presumed to have profibrotic role across species and tissues 24-26." (PMID 38505612, 2024).
acne (9 papers, 2023 to 2025). An inflammatory process of the sebaceous glands which is characterized by comedones, nodules, papules and/or pustules on the skin. "Given that TREM2 macrophages have been implicated in driving inflammation in acne, our subsequent analyses focused on the function of GRN within these cells." (PMID 39143467, 2024). "In a model of acne lesions caused by Cutibacterium acnes, excess production of squalene by hair follicle epithelium increases TREM2 expression in surrounding macrophages and induces TREM2-positive macrophages to enhance the phagocytosis of lipids and C. acnes." (PMID 38236825, 2024). "The sebum of acne patients has a higher content of squalene, which can increase TREM2 expression on macrophages." (PMID 38357543, 2024). "utilized single-cell transcriptome analysis to demonstrate the enhanced specificity and abundance of TREM2-expressing macrophages at the site of skin lesions in acne patients." (PMID 38736879, 2024). "In acne lesions, excessive squalene production by keratinocytes and sebocytes triggers TREM2 macrophage differentiation, enhancing immune cell migration and fueling the inflammatory cascade." (PMID 39143467, 2024). "These foam cells express TREM2 and infiltrate in acne lesions." (PMID 38357543, 2024). "Interestingly, TREM2 macrophages-recruited mast cell, NKT cell, T cell and neutrophils, all capable of secreting IL-1383, 84, this connection bridges inflammation and hyperkeratinization processes in acne, indicating that inflammation precedes and triggers hyperkeratinization." (PMID 38854033, 2024). "Interestingly, TREM2 macrophages-recruited mast cell, NKT cell, T cell and neutrophils, all capable of secreting IL-13, this connection bridges inflammation and hyperkeratinization processes in acne, indicating that inflammation precedes and triggers hyperkeratinization." (PMID 39143467, 2024).
Leukoencephalopathy (9 papers, 2009 to 2025). This term describes abnormality of the white matter of the cerebrum resulting from damage to the myelin sheaths of nerve cells. "Individuals with homozygous loss of function of TREM2 display Nasu–Hakola disease, in which leukoencephalopathy is a prominent feature." (PMID 39778705, 2025). "The white matter volume differences are of interest as other TREM2 variants are associated with leukoencephalopathy." (PMID 37990275, 2023). "In our analyses, TREM2, TYROBP, and GRN associated with leukoencephalopathy and FTD, show correlated gene expression, however, SMCR8 and WDR41, known to form a complex with C9orf72, did not." (PMID 38469573, 2024).
myocardial infarction (9 papers, 2023 to 2025). Gross necrosis of the myocardium, as a result of interruption of the blood supply to the area, as in coronary thrombosis. "Recent preclinical studies have shown that immediate intramyocardial injection of recombinant adenovirus encoding full-length mouse TREM2 or sTREM2 significantly improves cardiac function in mice with myocardial infarction following ligation of the left anterior descending (LAD) coronary artery." (PMID 40083551, 2025). "In human myocardial infarction samples, about half of TREM2-expressing macrophages also co-express SPP1, indicating a shared phenotype involved in tissue repair and remodeling." (PMID 40520014, 2025). "A recent review has highlighted TREM2’s protective role in the heterogenous population of macrophages during inflammation following myocardial infarction." (PMID 40083551, 2025). "It has recently been shown that TREM2 expression is significantly upregulated in cardiac tissue after myocardial infarction in mice." (PMID 40639905, 2025). "Additionally, TREM2 is involved in the clearance of necrotic myocardial cells after acute myocardial infarction and the removal of lipid-rich apoptotic hepatocytes in non-alcoholic steatohepatitis (NASH)." (PMID 40242752, 2025). "PERTINENT FINDINGS: It has been demonstrated that the normalization of PET data to account for blood levels enhances the detection of TREM2 levels in the periphery of WT mice, in the brain of a mouse model of AD, and in the heart of a mouse model of myocardial infarction." (PMID 40639905, 2025). "TREM2 has been proven to participate in phagocytosis and metabolism, but how it modulates myocardial infarction remains unclear." (PMID 38182899, 2024). "Interestingly, single-cell RNA sequencing of cardiac immune cells also revealed upregulated Trem2 expression in subpopulations of macrophages in animal models of myocardial infarction (MI), hypertension-induced heart failure with preserved function (HFpEF), and septic cardiomyopathy." (PMID 40083551, 2025). "In cardiovascular disease research, especially in the fields of myocardial infarction (MI), sepsis-induced cardiomyopathy (SICM), and heart failure (HF), the role of TREM2 in cardiac macrophages is gaining increasing attention." (PMID 40242752, 2025). "Collectively, these findings highlight the significance of TREM2 as a critical regulator of the efferocytosis-TCA cycle-immune metabolites axis in macrophages, suggesting its potential as a promising therapeutic target for restoring cardiac function after myocardial infarction." (PMID 38182899, 2024).
renal cell carcinoma (9 papers, 2020 to 2025). "Our results also clarified that up-regulation of TREM2 expression is associated with poor prognosis in patients with renal cancer, and previous studies have demonstrated that TREM2 acts as an oncogene in the development of renal cell carcinoma." (PMID 33679809, 2021). "Downregulation of TREM2 in renal cell carcinoma blocks the G1 phase and promotes apoptosis of tumor cells, and thus inhibits tumor development." (PMID 38910324, 2024). "Similarly, we detected TREM-1 and Trem2 expression in myeloid cells in the RENCA model of renal cell carcinoma (RCC)." (PMID 35223446, 2021). "As for renal cell carcinoma (RCC), research has shown that the expression level of TREM2 in RCC tumor tissues was abnormally elevated, and that TREM2 exerts a crucial oncogenic effect by modulating apoptosis-related proteins and the PTEN-PI3K/AKT signaling pathway." (PMID 40242752, 2025).
Arthritis (8 papers, 2016 to 2025). Inflammation of a joint. "Furthermore, NF-κB signaling pathway inhibition significantly suppressed arthritis inflammation in OA mice, thereby effectively alleviating TREM2 deficiency-related adverse effects on chondrocytes." (PMID 38617547, 2024). "In recent years, research on the role of macrophage TREM2 in arthritis has also been gradually conducted." (PMID 38617547, 2024). "The high expression of TREM2 in macrophages has significant implications for the recovery and treatment of arthritis, thus making it extremely urgent to conduct in-depth research on this process." (PMID 38617547, 2024). "In this study, we showed that in experimental arthritis, inhibiting TREM-2 ameliorated arthritis and significantly reduced cartilage and joint damage, similarly to what happens when inhibiting TREM-1." (PMID 36012120, 2022). "However, to the author’s knowledge, no studies have yet investigated the effect of inhibition of TREM-2 in experimental arthritis." (PMID 36012120, 2022). "We demonstrated that administration of IA9, but not a control peptide, after induction of arthritis diminished release of proinflammatory cytokines and dramatically suppressed joint inflammation and damage, suggesting that targeting TREM-2 may be a promising approach for the treatment of RA." (PMID 36012120, 2022).
colitis (8 papers, 2014 to 2025). Inflammation of the colon. "In this context, genetic ablation of TREM-2 is associated with protection against colitis, along with the reduced secretion of pro-inflammatory cytokines and matrix metalloproteinases expression." (PMID 31546668, 2019). "Thus, similar to TREM-1, TREM-2 may foster the progression of colitis-associated cancer by controlling epithelial proliferation during colonic injury and inflammation." (PMID 31546668, 2019). "Simultaneously, reduced disease severity and lower levels of inflammatory cytokines are reported in TREM2-knockout colitis mice." (PMID 39405126, 2024). "On the other hand, TREM-2-KO animals have less severe colitis, reduced cytokine production in the colon, along with a reduced number of mitotic epithelial cells and advanced carcinomas." (PMID 31546668, 2019). "In network analyses, TREM2 was significantly co-enriched with DOCK2 and DOCK8 which are involved in tissue transmigration and mice deficient for TREM2 had reduced leukocyte infiltration following experimental induction of colitis." (PMID 28768545, 2017). "Due to the peculiar activities of TREM-1 and TREM-2 in controlling bacterial infection, the functional role of these two receptors has also been studied in IBD patients and in experimental models of colitis." (PMID 25347935, 2014). "The absence of TREM-2 in intestinal lamina-propria DCs was likewise shown to lead to a reduced production of pro-inflammatory cytokines and mitigation of T-cell activation during experimental colitis." (PMID 25347935, 2014).